BRCA2 (BRCA2 DNA repair associated)
Diseases named in the same sentence as BRCA2 in open-access papers (continued):
Sharing a sentence is not in itself a finding about the gene and the disease.
Hereditary breast and ovarian cancer syndrome (continued). "The BRCA2 c.156_157insAlu mutation, which accounts for 37.9% of all mutations in families with hereditary breast and ovarian cancer (HBOC) in Portugal, is carried by a Portuguese haplotype occasionally found in countries of Portuguese immigration." (PMID 26618902, 2015). "Likely pathogenic BRCA2 variants were found in 2 individuals, which is consistent with the estimated general population prevalence of 1/400 of hereditary breast and ovarian cancer syndrome." (PMID 26332594, 2015). "Deleterious mutations inBRCA1 and BRCA2 genes are the only known causes of hereditary breast and ovarian cancer (HBOC) syndrome." (PMID 26557407, 2015). "Mutations in BRCA1 and BRCA2 are responsible for a large proportion of breast-ovarian cancer families." (PMID 23704879, 2013). "Germline inactivating mutations in BRCA1 and BRCA2 genes are responsible for Hereditary Breast and Ovarian Cancer Syndrome (HBOCS)." (PMID 23613828, 2013). "In 1996, the US-based biotechnology company Myriad Genetics began offering genetic diagnostic tests for mutations in the genes BRCA1 and BRCA2, which are linked to hereditary breast and ovarian cancer." (PMID 23885284, 2013). "Our findings indicate that both BRCA1 and BRCA2 mutations account for a substantial proportion of hereditary breast/ovarian cancer in the Southern Chinese population." (PMID 22970155, 2012). "A typical example is provided by the case of Ashkenazi Jews, where three founder mutations: BRCA1 c.66_67delAG BRCA1 c.5263insC, and BRCA2 c.5946delT account for most of familial breast-ovarian cancer." (PMID 23961350, 2012). "Genetic counseling and testing for BRCA1 and BRCA2 gene mutation has become an integral part of high-risk patient evaluation and management for hereditary breast ovarian cancer." (PMID 22382806, 2012). "Mutations of BRCA1 and BRCA2, common in hereditary breast and ovarian cancer (HBOC) syndrome, predispose carriers to developing breast, ovarian, and a variety of other cancers including PC." (PMID 22312493, 2011). "Germ-line mutations in the BRCA1 and BRCA2 genes are major contributors to hereditary breast/ovarian cancer." (PMID 21939546, 2011). "Germline mutations in the susceptibility genes BRCA1 and BRCA2 in hereditary breast/ovarian cancer, though low in prevalence, are highly penetrant and show geographical variations." (PMID 18662409, 2008). "The medical files of BRCA1 or BRCA2 mutation carriers and members of a hereditary breast/ovarian cancer (HBOC) family, who had undergone prophylactic surgery, were reviewed." (PMID 15083174, 2004). "A single mutation (6174delT) occurs in the BRCA2 gene in high-risk breast ovarian cancer families of Jewish Ashkenazi origin, in about 1% of the general Ashkenazi population, and rarely in non-Ashkenazi Jews." (PMID 11207041, 2001). "We also typed 124 affected and 276 unaffected female carriers with known deleterious BRCA1 or BRCA2 germline mutation from high-risk breast-ovarian cancer families." (PMID 10487631, 1999). "Pathogenic germline variants in the BRCA1 and BRCA2 genes predispose individuals to HBOC syndrome." (PMID 39980563, 2025). "BRCA2 is a causal gene for hereditary breast and ovarian cancer (HBOC) syndrome." (PMID 40462315, 2025). "Furthermore, a mutation in germline BRCA2 was detected postoperatively, and the patient was finally diagnosed with hereditary breast and ovarian cancer syndrome." (PMID 37592269, 2023).
Hereditary breast and ovarian cancer syndrome (continued). "This patient harboring a pathogenic BRCA2 variant, p.Arg2520* (ClinVar Variation ID: 52353), which has been observed in several individuals with hereditary breast-ovarian cancer (HBOC), prostate, pancreatic, esophageal and renal cancer from diverse ethnic origins." (PMID 37323311, 2023). "Discoveries in observational studies and family studies led to the determination of genetic factors involved in EOC risk, notably those associated with the so-called hereditary breast and ovarian cancer (HBOC) syndrome caused by germline mutations in BRCA1 or BRCA2 (BRCA1/2)." (PMID 35267439, 2022). "As suggested by Pritchard (2019) the terminology of the syndrome itself—BRCA1- and BRCA2-associated Hereditary Breast and Ovarian Cancer syndrome–is considered misleading and should be changed because it induces the false belief that BRCA1/2 mutations are "women’s business" only." (PMID 35303741, 2022). "Genetic testing should also be considered for all patients with a diagnosis of gastric neoplasia and a family history compatible with Lynch syndrome, FAP, Peutz–Jeghers, Li–Fraumeni, juvenile polyposis, hereditary breast and ovarian cancer syndrome (germline mutations in BRCA1 or BRCA2)." (PMID 33804024, 2021). "Germ-line mutations in the BRCA2 gene predispose to high risk of breast and ovarian cancer (BOC)." (PMID 21939546, 2011). "Overall, 8 distinct BRCA1 and 5 distinct BRCA2 pathogenic mutations were found in 35 (10%) out of 348 breast-ovarian cancer families; 11 "high-risk" families were positive for BRCA1 and 12 for BRCA2, whereas 1 BRCA1 and 11 BRCA2 mutations were identified in "no high-risk" families." (PMID 19619314, 2009). "Finally, a comparison was made between the frequency of BRCA2 mutations in this study population compared to the frequency of BRCA2 mutations in breast ovarian cancer families." (PMID 12373604, 2002). "Our results show the prevalence of the germline BRCA2 pathogenic variant c.7561delA, p.(Ile2521SerfsTer3) among individuals recruited in the Rimini district, Italy, consistent with being a high-risk population for HBOC syndrome and for PDAC, for which we calculated the risk of occurrence." (PMID 37046793, 2023). "Furthermore, performance of the ‘PROBA RC’ could be further increased by incorporating other risk factors, for example, family history of BRCA2 mutation, hereditary breast and ovarian cancer, and Lynch syndrome." (PMID 35356754, 2022). "Hereditary breast and ovarian cancer syndrome (HBOC) is principally caused by germline mutations in BRCA1 and BRCA2." (PMID 41876608, 2026). "One BRCA2 pathogenic variant carrier and one CHEK2 LP variant carrier met the testing criteria for HBOC syndrome." (PMID 40446793, 2025). "For instance, the ATM gene is well-known as the third most frequently mutated gene in hereditary breast and ovarian cancer (HBOC) after BRCA1 and BRCA2." (PMID 41022541, 2025). "Germline pathogenic variants of HR-related genes, such as BRCA1 and BRCA2 (BRCA1/2), cause hereditary breast and ovarian cancer syndrome (HBOC)." (PMID 40224668, 2025). "HBOC syndrome is a cancer susceptibility syndrome caused by germline mutations in BRCA1 and/or BRCA2 and is inherited in an autosomal dominant manner." (PMID 39590127, 2024). "In an effort to identify PGVs on other HBOC syndrome causative genes, all selected probands were wildtype for BRCA1/BRCA2 alleles." (PMID 39003386, 2024). "Pathogenic TE insertions are associated with various hereditary cancers, including hereditary breast and ovarian cancer syndrome (BRCA1, BRCA2, and BARD1); Lynch syndrome (MLH1); and colorectal cancer (APC)." (PMID 39697868, 2024). "PGV prevalence was assessed for 682 BRs of 281 probands with BRCA1/BRCA2 wild-type hereditary breast and ovarian cancer (HBOC) syndrome." (PMID 39003386, 2024). "The most common cause of hereditary breast and ovarian cancers (HBOC) is the presence of mutations in the BRCA1 and BRCA2 genes." (PMID 37685988, 2023).
Hereditary breast and ovarian cancer syndrome (continued). "Approximately 30–50% of hereditary breast and ovarian cancer (HBOC) is due to the presence of germline pathogenic variants in the BRCA1 (OMIM 113705) and BRCA2 (OMIM 600185) onco-suppressor genes, which are involved in DNA damage response." (PMID 37958491, 2023). "In patients with hereditary breast and ovarian cancer (HBOC) syndrome, who are heterozygously mutated in either BRCA1 or BRCA2, cancer‐initiating cells mostly undergo loss of wild‐type BRCA1/2 allele." (PMID 36345163, 2023). "This involves variants in the genes BRCA1 (n = 1; FAM215) and BRCA2 (n = 2; FAM91; FAM209), which are associated with an increased risk of hereditary breast and ovarian cancer (HBOC)." (PMID 37274821, 2023). "The most frequently covered health condition of interest was BRCA1/BRCA2 genetic testing (n = 19) for hereditary breast and ovarian cancer (HBOC)." (PMID 37531363, 2023). "BRCA1 gene mutations cause familial breast-ovarian cancer-1 (BROVCA1), and BRCA2 gene mutations cause familial breast-ovarian cancer-2 (BROVCA2)." (PMID 36835955, 2023). "The German Consortium for Hereditary Breast and Ovarian Cancer (GC-HBOC) conducted a comprehensive BRCA screening and revealed a higher mutation frequency in BRCA1 than that in BRCA2." (PMID 36232564, 2022). "Germline mutations consistent with hereditary breast and ovarian cancer syndrome (HBOC), in BRCA1 and BRCA2, were found in four patients." (PMID 36359225, 2022). "In our cases, neoplasms arose in the context of HBOC syndrome due to BRCA2 alteration and in the context of Peutz–Jeghers syndrome." (PMID 36056133, 2022). "BRCA1 and BRCA2 with other homologous recombination genes are the most tested genes in hereditary breast and ovarian cancer (HBOC) patients." (PMID 36171877, 2022). "BRCA1 and BRCA2 are considered major cancer predisposing genes as they account for a significant proportion of HBC and HBOC syndrome families in all studied populations." (PMID 34298626, 2021). "Detection of mutations in hereditary breast and ovarian cancer related BRCA1 and BRCA2 genes is an effective method of cancer prevention, early detection, and treatment." (PMID 34490083, 2021). "Based on ClinVar annotation, rs397507634 in BRCA2 is related to hereditary breast and ovarian cancer syndrome (RCV000590670.1), breast-ovarian cancer, familial 2 (RCV000077282.4), and hereditary cancer-predisposing syndrome (RCV000213349.1)." (PMID 34367235, 2021). "In patients with breast-ovarian cancer, the gene BRCA2 has a high frequency of the “AAGA” deletion at cds.1310-1313." (PMID 32849737, 2020). "The role of germline mutations in the breast-ovarian cancer predisposition genes BRCA1 and BRCA2 in the risk of familial melanoma development is still a matter of debate and the exact melanoma risk increase (if any) in mutation carriers is uncertain." (PMID 33050356, 2020). "In the mid-1990s, BRCA1 and BRCA2 which are part of the DNA-repair machinery were identified to play a crucial role in hereditary breast and ovarian cancer (HBOC)." (PMID 31395037, 2019). "It is noteworthy that large rearrangements in BRCA1and BRCA2 accounted for less than 1% of evaluated patients suffering from hereditary breast and ovarian cancer." (PMID 30975222, 2019).
Hereditary breast and ovarian cancer syndrome (continued). "Between 5 and 10% of all BC and 13–15% of OC are hereditary and approximately 25% are associated with the Hereditary breast/ovarian cancer (HBOC) syndrome, caused by abnormalities in the DNA repair genes BRCA1 and BRCA2." (PMID 31771539, 2019). "Hereditary breast and ovarian cancer syndrome most frequently occur through inheritance of mutations in the BRCA1 and BRCA2 genes." (PMID 29659587, 2018). "The aim of this study was to identify genomic alterations in BRCA1/BRCA2 wild-type tumor samples from women with family history strongly suggestive of hereditary breast/ovarian cancer." (PMID 29938003, 2018). "Hereditary breast and ovarian cancer syndrome, caused by a germline pathogenic variant in the BRCA1 or BRCA2 (BRCA1/2) genes, is characterized by an increased risk for breast, ovarian, pancreatic and other cancers." (PMID 27375968, 2016). "Different laboratories have implemented NGS to analyze BRCA1 and BRCA2 or panels of candidate genes suspected as being involved in Hereditary Breast Ovarian Cancer (HBOC)." (PMID 27793035, 2016). "Because constitutional BRCA2 and MLH1 gene mutations are associated with Hereditary Breast Ovarian Cancer Syndrome (HBOCS) and Lynch syndrome respectively, sequence analysis of DNA isolated from peripheral blood was performed." (PMID 25712765, 2015). "Specific germline mutations in the hereditary breast-ovarian cancer susceptibility (HBC/HBOC) genes, BRCA1, BRCA2 and PALB2, have been shown to recur in French Canadians of Quebec, Canada, and this has been attributed to common ancestors." (PMID 25925845, 2015). "Germ line mutations in BRCA1 and BRCA2 (BRCA1/2) and other susceptibility genes have been identified as genetic causes of hereditary breast and ovarian cancer (HBOC)." (PMID 24884479, 2014). "In the present study, a germline pathogenic mutation in either BRCA1 or BRCA2 was identified in 10% of screened breast-ovarian cancer families (BRCA1 mutations were detected in about 3% of cases, while BRCA2 mutations were identified in about 7% of families)." (PMID 19619314, 2009). "Genomic DNA from 348 probands of breast-ovarian cancer families was screened for germline mutations in BRCA1 and BRCA2 genes." (PMID 19619314, 2009). "This contrasts to the situation with another breast-ovarian cancer gene, BRCA2, whose homozygous inactivation leads to Fanconi anemia but is not absolutely lethal." (PMID 19338681, 2009). "Several genes conferring susceptibility to breast and ovarian cancer, notably BRCA1 and BRCA2, have been identified." (PMID 15381934, 2004). "This study indicates a BRCA2 contribution of 10% (95% CI 2.5–17.5) to our original cohort of 59 breast-ovarian cancer families, whereas the contribution of BRCA1 had been estimated at 46% (95% CI 33–59)." (PMID 11207042, 2001). "Melanoma risk is also thought to be increased in cancer predisposition syndromes including Cowden syndrome, Li-Fraumeni syndrome, and hereditary breast and ovarian cancer syndrome, caused by pathogenic variants in phosphatase and tensin homolog, tumor protein 53, and BRCA1 and BRCA2, respectively." (PMID 39188332, 2024). "However, women with HBOC syndrome, on average, experience menopause earlier than usual, and based on genome-wide association studies, it is known that being a carrier of BRCA1 or BRCA2 gene mutation is related with increased ovarian aging." (PMID 39061239, 2024). "Detection of pathogenic variants with varying penetrance in the BRCA1 and BRCA2 genes are responsible for approximately two-thirds of hereditary breast and ovarian cancer, with cumulative risks ranging from 16–84% and 11–87% for BRCA2 and BRCA1, respectively, by age 80 years." (PMID 36568162, 2022).
Hereditary breast and ovarian cancer syndrome (continued). "As shown in an early targeted analysis of 20 variants in FCs, 84% of BRCA1 and BRCA2 positive HBC and HBOC syndrome families harbour one of five specific PVs in these genes accounting for the high frequency of these PVs observed in BC- and OC-affected individuals in this population." (PMID 34298626, 2021). "For example, hereditary breast and ovarian cancer (HBOC) syndrome is a hereditary syndrome associated with a high risk of breast and ovarian cancer that is caused by pathological alterations of the BRCA1 or BRCA2 gene in germline cells." (PMID 33249514, 2021). "In this regard, the aim of this study was to identify chromosomal and subchromosomal copy number alterations in tumor samples from Brazilian women without BRCA1/BRCA2 germline mutations with family history strongly suggestive of HBOC syndrome." (PMID 29938003, 2018). "Until present, squamous cell carcinomas of the pancreas have never been described in the context of germ line BRCA2 mutations or within the tumor spectrum of the HBOC syndrome." (PMID 24959366, 2014). "We examined seven cases from breast-ovarian cancer families with tumours that showed BRCA1-like pathology but did not have detectable BRCA1 or BRCA2 germline mutations present." (PMID 18269736, 2008). "FA caused by biallelic pathogenic variants (PVs) in BRCA2/FANCD1 (OMIM *600185) accounts for only about 3% of FA cases, but it is clinically significant because it relates the underlying FA/BRCA pathway defect to hereditary breast and ovarian cancer (HBOC), due to monoallelic BRCA2 PVs." (PMID 40724944, 2025). "For example, identification of a somatic pathogenic variant in the BRCA1 or BRCA2 genes following tumor profiling may lead to personalized treatment with a PARP inhibitor, but it may also be indicative of Hereditary Breast and Ovarian Cancer syndrome if present in the germline." (PMID 39238026, 2024). "Although this ancestry is associated with an increased risk of a pathogenic genetic variant in BRCA1/BRCA2, it is not the only pathogenic variant associated with Hereditary Breast and Ovarian Cancer Syndrome despite the emphasis it receives in practice guidelines." (PMID 37626335, 2023). "An analysis of the risk of BRCA2 mutations for development of other cancers in 173 breast-ovarian cancer families found a five-fold increased relative risk of CaP, which increased to seven-fold among men below the age of 65 among BRCA2 mutation carriers compared with non-carriers." (PMID 29690565, 2018). "However, other than germline BRCA1 or BRCA2 mutations, which are related to hereditary breast-ovarian cancer (HBOC), cancer-predisposition genes have not been well studied in this population." (PMID 28961279, 2017). "Furthermore, BRCA1 mutations were strongly associated with hormone-receptor negative status in previous analyses of high-risk breast-ovarian cancer families whereas most BRCA2-mutated tumours do not have a TNBC phenotype." (PMID 23110154, 2012). "FA is an inherited bone marrow failure syndrome caused by defects in any one of so far identified 22 FANC genes including hereditary breast and ovarian cancer (HBOC) genes BRCA1 and BRCA2." (PMID 36345163, 2023). "A representative hereditary tumor due to germline deficiency of HR, which is represented by alterations in BRCA1 or BRCA2 (BRCA1/2), is the hereditary breast and ovarian cancer (HBOC) syndrome." (PMID 35008774, 2021). "A total of 95 individuals with HBOC syndrome clinical suspicion in Southeast Brazil were sequenced, and 25 samples were evaluated for insertions/deletions in BRCA1/BRCA2 genes." (PMID 32039725, 2020). "In this study, we screened 95 samples of patients with HBOC syndrome clinical suspicion, using a multi-gene panel sequencing both flanking and coding regions of BRCA1, BRCA2 and another 19 DNA repair genes." (PMID 32039725, 2020).